STAT3 (signal transducer and activator of transcription 3)
Diseases named in the same sentence as STAT3 in open-access papers (continued):
Sharing a sentence is not in itself a finding about the gene and the disease.
epilepsy (38 papers, 2015 to 2026). A brain disorder characterized by episodes of abnormally increased neuronal discharge resulting in transient episodes of sensory or motor neurological dysfunction, or psychic dysfunction. "Quantitative real-time PCR (qRT-PCR) was performed to assess Klotho and epilepsy-associated gene expression (STAT3, Bax, Bcl2)." (PMID 40351444, 2025). "Inflammatory pathways, including those involving STAT3, have been implicated in preclinical studies in the modulation and genesis of epilepsy after brain injury." (PMID 38166692, 2024). "In epilepsy, the upregulation of miR-21-5p inhibited STAT3 expression and reduced apoptosis and the loss of hippocampal neurons, thereby achieving protective effects on hippocampal neurons of epileptic rats." (PMID 35173580, 2022). "Therefore, miR-21-5p is able to suppress expression of STAT3, decrease IL-6 levels and reduce loss of hippocampal neurons, thus protecting hippocampal neurons from deteriorating effects of epilepsy." (PMID 35088379, 2022). "Inhibiting STAT3 signaling could improve the prognosis of animal models with temporal lobe epilepsy, and simultaneously prevent the pathogenic changes in the neural circuits behind epilepsy." (PMID 38443733, 2024). "Interestingly, both FGFR3 and STAT3 have been associated with epilepsy." (PMID 33002329, 2020). "Molecules with optimized pharmacokinetic properties selectively aimed at the inhibition of STAT3 phosphorylation in brain have recently emerged as potential disease modifying therapies for epilepsy." (PMID 39643584, 2025). "Recently, studies from our groups have shown that genetic- or pharmacologic-mediated inhibition of STAT3 at the time of brain injury induced by status epilepticus (SE), reduces the severity of subsequent epilepsy in rodent models." (PMID 39643584, 2025). "In human epilepsy, serum levels of all STATs are elevated, with STAT3 being the most profound at a nine-fold increase above baseline." (PMID 38166692, 2024). "It was confirmed that miR-146a directly binds and downregulates the transcription factor Krüppel-like factor 4 (KLF4) to activate STAT3 and mediate epilepsy seizures by affecting synaptic plasticity in the pentylenetetrazole-kindling mouse model of epilepsy." (PMID 37213914, 2023). "Signal transducer and activator of transcription 3 (STAT3) is highly expressed in children with epilepsy." (PMID 36531133, 2022). "It has been reported that let-7b is downregulated in children with autism and that it can target STAT3 and inhibit hippocampal glial cell activation in epilepsy." (PMID 34471635, 2021). "Both the phosphorylation and total expression of STAT3 is increased in tissue samples resected from patients with epilepsy due to hippocampal sclerosis, focal cortical dysplasia, and tumors." (PMID 34122302, 2021). "We further explored the role of Stat3 in glial cell activation in epilepsy using the Stat3 inhibitor, AG490." (PMID 32648622, 2020). "Activation of all STATs was elevated in epilepsy, and STAT3 was activated 9-fold in average, which was the highest among all STATs." (PMID 26626560, 2015). "Meanwhile, we found that epilepsy phenotype was reduced after STAT3 activation was inhibited." (PMID 39994587, 2025). "This suggests that CPEB3 may alters the epilepsy phenotype by inhibiting the transcriptional activity of STAT3." (PMID 39994587, 2025). "An epilepsy study suggests that the STAT3 pathway regulates synaptic plasticity in epileptic mice." (PMID 41428145, 2025). "To verify whether CEPB3 can regulate STAT3 expression in epilepsy, we examined changes in STAT3 in total protein lysates from mouse hippocampal tissue." (PMID 39994587, 2025). "As hyperactivation of STAT3 is a known driver of epilepsy, STAT3 (and NF-κB) might be connected to the neurological symptoms associated with TSC." (PMID 39070657, 2024). "In a rat model of epilepsy, it was found that miR-21-5p binds to STAT3." (PMID 37653173, 2023).
epilepsy (continued). "Another experiment in a rat model of epilepsy has shown that miR-21-5p can bind to STAT3." (PMID 35088379, 2022). "In an epilepsy rat model, it is known that STAT3 is activated after status epilepticus." (PMID 33050466, 2020). "Uncovering the mechanism of this novel form of BDNF signaling in the brain may provide a new direction for epilepsy therapeutics and open a window into the complex mechanisms of STAT3 transcriptional regulation in neurological disease." (PMID 31455240, 2019). "All STATs were activated in epilepsy, among which, STAT3 was the most activated one." (PMID 26626560, 2015). "Activation of STATs, especially STAT3, was important in epilepsy." (PMID 26626560, 2015). "Pending functional validation, these findings identify STAT3 as a pathway of interest and a potential therapeutic candidate, supporting the development of adjunctive anti-inflammatory therapies targeting neuroimmune cascades for DS and broader refractory epilepsies." (PMID 42051563, 2026). "Consequently, we speculated that CPEB3 can reduce STAT3-mediated transcription of NMDARs by inhibiting STAT3 translation in epilepsy." (PMID 39994587, 2025). "In addition, overexpression of BDNF in cortical neurons from Sip1 mice resulted in increased expression of Bcl-2, Socs3 and Stat3 genes, which may contribute to the protection of neurons from injury in epilepsy." (PMID 39408863, 2024). "Further mechanistic studies revealed that exogenous overexpression of CPEB3 inhibited STAT3 translation and STAT3-mediated transcriptional activity of NMDARs, thereby suppressing NMDAR subunit expression and attenuating epilepsy phenotype in mice." (PMID 39994587, 2025). "STAT3, another member of the STAT protein family, has been demonstrated to be involved in the regulation of epilepsy." (PMID 40857409, 2025). "Therefore, STAT3 could serve as an effective anti-epilepsy target." (PMID 38443733, 2024). "We identified and characterized the dynamics of a CSF1R-regulating GRN in epilepsy and validated STAT1 and STAT3 as main regulators of this GRN." (PMID 33819288, 2021). "Among all STAT members, STAT3 activation level was increased ninefold in average, much higher than other STAT members (3–5 fold), indicating potential critical role of STAT3 in epilepsy." (PMID 26626560, 2015). "STAT3, a transcription factor involved in neuroinflammation and apoptosis, was significantly upregulated in PTZ-treated mice, consistent with previous reports on its role in epilepsy-induced neuroinflammation." (PMID 40351444, 2025). "We performed qPCR experiments and immunohistochemistry on tissue microarrays containing 286 GBMs to further explore the association of these candidate pathways and of markers of mesenchymal transformation (NF-κB, CEBP-β, STAT3, STAT5b, VEGFA, SRF) with epilepsy." (PMID 30621209, 2019). "We injected WP1066 (a STAT3 inhibitor) intraperitoneally into knockdown CPEB3 mice and examined the protein and mRNA expression of GluN1, GluN2A, and GluN2B to verify whether CPEB3 inhibits the transcriptional activity of NMDARs via STAT3 in epilepsy." (PMID 39994587, 2025). "In these studies, Gabra1 regulation via ICER is independent of STAT3 phosphorylation, suggesting that neuronal signaling through both the canonical and non-canonical pathways may be relevant to epilepsy, and potentially to learning and memory." (PMID 39643584, 2025). "Indeed, inflammatory mediators may be relevant for the pathogenesis of epilepsy in FCD, as confirmed by the reported up-regulation of inflammatory cytokines and their receptors and/or downstream effectors (such as IL-1β, IL-6, CCL3, CCL4, STAT3, C-JUN and CCR5) in this disease." (PMID 35741692, 2022). "Additionally, a gene set containing STAT5 targets (p < 0.0001, FDR = 0.06) and gene sets involved in CEBP-β, STAT3 signaling and epithelial to mesenchymal transition (EMT) signaling (p < 0.05, FDR < 0.25) were downregulated in the epilepsy subgroup compared to patients without epilepsy." (PMID 30621209, 2019).
Hepatitis (38 papers, 2011 to 2025). Inflammation of the liver. "Kahweol's anti‐inflammatory effect on liver inflammation was found to be associated with reduced expression of phospho‐NF‐kB and phospho‐STAT3." (PMID 40066227, 2025). "Our findings underscore the critical role of ROS-dependent Jak2/Stat3 pathway activation in the occurrence of HBV-induced liver inflammation, providing new insights into the pathogenesis of chronic hepatitis B." (PMID 42290660, 2025). "This study comprehensively elucidates the molecular mechanism by which threonine regulates lipid synthesis and metabolism in the duck liver through STAT3, providing a basis for the nutritional prevention of hepatic lipid metabolic disorders." (PMID 39125712, 2024). "In the carbon tetrachloride and alcohol models of acute liver injury, the inflammatory index was found to be lower in STAT3-knockout mice, while the inflammatory index was higher in the ConA-induced hepatitis and LPS-induced models of STAT3-knockout mice." (PMID 36761734, 2023). "The use of IFN-α to treat hepatitis-positive HCCs can activate a parallel STAT3-mediated NF-κB signaling pathway." (PMID 33805945, 2021). "The activation of STAT1 (pSTAT1) and STAT3 (pSTAT3) plays a pivotal role in controlling liver steatosis and liver inflammation." (PMID 34112940, 2021). "On the other hand, transactivation of the complexes IL-6/STAT3/lncTCF7 or IL-6/STAT3/Snail-Smad3/TGF-β1 promotes the invasion of HCCs developed in patients with hepatitis, especially the nonalcoholic type." (PMID 31781608, 2019). "They further showed that phosphorylated Stat3 and IL-6 were reduced in ConA-induced hepatitis, whereas p21 and Smad2 increased." (PMID 28330461, 2017). "It has been reported that IL-22 induces STAT3 activation in the liver and IL-22 blockade significantly reduces hepatic STAT3 activation in T cell-mediated hepatitis." (PMID 29383167, 2017). "Pharmacological inhibition of Stat3 activity within the liver blocked the ability of IL-6 to prevent liver inflammation and to normalize the T/HS-induced liver inflammation transcriptome." (PMID 21738667, 2011). "Genetic deletion of a Stat3β, a naturally occurring, dominant-negative isoform of the Stat3, attenuated T/HS-induced liver inflammation, confirming a role for Stat3, especially Stat3α, in preventing T/HS-mediated liver inflammation." (PMID 21738667, 2011). "In this report, the authors indicate that the deletion of STAT3 in myeloid cells, including leukocytes, enhances inflammation in concanavalin A-induced hepatitis." (PMID 22136659, 2011). "Moreover, IL-6 is associated with the protein level of PHB1 in hepatitis; however, the role of the PHB1/IL-6/STAT3 signalling pathway in the development of hepatitis is controversial." (PMID 35847581, 2022). "Furthermore, hypoxia‐induced activation of JAK2/STAT3 was inhibited by salidroside treatment, which is possibly a potential mechanism to ameliorate hypoxia‐induced liver inflammation." (PMID 34532015, 2021). "IL-6 was also involved in the induction of BNIP3 through the activation of Jak/Stat3 signaling, and the suppression of IL-6/Jaks/Stat3 signaling might contribute to the inhibition of Bnip3-mediated apoptosis and autophagy in ConA-induced hepatitis." (PMID 30177931, 2018). "Similar to bowel inflammation, Stat3′s contribution to liver inflammation is influenced in a cell-type specific fashion that may functionally compete, depending on the cell type and the model of liver injury." (PMID 21738667, 2011). "Moreover, IL-22/STAT3 has an anti-fibrotic function in T cell-mediated murine hepatitis." (PMID 27819314, 2016). "Particularly, evidence confirms that STAT3 is a critical anti‐inflammatory signal in MAFLD, regulating MAFLD‐induced liver inflammation and fibrosis." (PMID 40066227, 2025).
Hepatitis (continued). "The mechanism underlying its induction of hepatitis may be associated with the activation of noncanonical nuclear factor-κB (NF-κB), signal transducer and activator of transcription 3 (Stat3), and the mammalian family of mitogen-activated protein kinases (MAPKs)." (PMID 39290976, 2024). "In a model of concanavalin A-induced hepatitis, activated STAT1 exacerbates its induction of hepatitis, whereas activated STAT3 attenuated hepatitis." (PMID 36671504, 2023). "Our study demonstrated that APAP and ROX co-treatment significantly increased the expression levels of TNF-α, INF-γ, VCAM-1, CXCL-1, STAT-3, Nrf-2, GSTA, GCLC-1, HO-1 and NQO1, suggesting that APAP and ROX co-treatment can induce liver inflammation." (PMID 32132876, 2020). "STAT3 may inhibit inflammation by inhibiting STAT1, so STAT3 can inhibit the activation of the pro-inflammatory factor STAT1 in ConA-induced and LPS-induced hepatitis." (PMID 36761734, 2023). "By primarily activating the anti-inflammatory cytokine (IL-10) mediated JAK1/STAT3 signaling pathway, PAE also effectively reduced oxidative stress-induced liver inflammation while also reducing liver damage, as evidenced by the reductions in serum AST and ALT." (PMID 36139880, 2022). "The role of Stat3 activation downstream of IL-6 in the resistance to T/HS-induced liver inflammation has not been studied previously." (PMID 21738667, 2011). "Moreover, STAT3 could also be activated by several other factors including IL-22, IL-10, ECG and hepatitis viral proteins, suggesting that further well designed studies should be conducted to explore the association between them and the risk of ATDH." (PMID 25789467, 2015).
metastatic disease (38 papers, 2010 to 2026). "Our analysis of data from The Cancer Genome Atlas (TCGA) database suggests that decreased mRNA STAT3 levels are often associated with PTEN deletion or downregulation in metastatic tumors." (PMID 37573301, 2023). "Genes in the unfavorable signatures tended to activate the acute immune system response and angiogenesis, both of which are associated with metastatic disease and poor prognosis through a constitutively activated STAT3 pathway." (PMID 33414466, 2021). "To date, one study has found a significant association between STAT3 activation and metastatic disease in papillary thyroid carcinoma patients, whereas another has found that STAT3 activation was inversely correlated with thyroid tumor growth." (PMID 29125844, 2017). "Moreover, we demonstrated that loss of STAT3 and/or p14ARF is associated with progression to metastatic disease." (PMID 26198641, 2015). "Clinical LUAD specimens further validated the correlation between DOT1L expression, STAT3 activation, and checkpoint upregulation, particularly in metastatic disease." (PMID 41836439, 2026). "The expression of IL-6, IL-6ST, and p-STAT3 (Tyr705) were significantly lower in FXR-silenced H1975 metastatic tumors than in corresponding control metastatic tumors." (PMID 38360812, 2024). "Loss of Stat3 in a Pten-null mouse prostate model leads to a reduction of LKB1/pAMPK with simultaneous activation of mTOR/CREB, resulting in metastatic disease." (PMID 37573301, 2023). "Tumorigenesis of CRC is involved with the transformation of normal colorectal epithelium to an invasive and metastatic tumor in response to chronic stimulation of inflammation, which is considered to be triggered by STAT3." (PMID 36266267, 2022). "Our own recent findings have found high levels of pSTAT3705 in bone, lymph node, and other organ metastases, thus further highlighting the role of STAT3 activation in metastatic disease." (PMID 30905090, 2019). "Among them, HOXD10 and PGR are specific to primary tumor, while STAT3, JUN and JUNB are associated to metastatic tumor based on our integrative regulatory network and survival analysis." (PMID 28005952, 2016). "STAT3 represents a particular promising target in this tumor entity, because, especially for patients with recurrent or metastatic disease, RT can be combined with an EGFR inhibitor, as activation of EGFR signaling commonly stimulates STAT3 phosphorylation." (PMID 25268165, 2014). "We further examined the STAT-3 phosphorylation in peritoneal metastatic tumors isolated from nude mice inoculated with MKN45 cells with or without honokiol (5 mg/kg) treatment." (PMID 22937084, 2012). "Moreover, Z-GS also decreased the expression of FXR, IL-6, IL-6ST, and p-STAT3 (Tyr705) in FXR-overexpressed A549 metastatic tumors." (PMID 38360812, 2024). "Constitutive activation of Stat3 in Ptenpc−/− mice significantly prolonged survival and decreased prostate tissue weight, in sharp contrast to Ptenpc−/− Stat3pc−/− mice that died rapidly from metastatic disease." (PMID 37573301, 2023). "Additionally, it is well established that increased STAT3 activation correlates with both advanced metastatic disease and worse survival in RCC." (PMID 30863721, 2019). "Constitutive activation of STAT-3 has been found in invasive and metastatic tumors." (PMID 30373171, 2018). "STAT3 is an attractive therapeutic target for both the early stages and metastatic disease." (PMID 27835873, 2017). "For example, in the metastatic tumors five miRNAs (miR-671-5p, miR-665, miR-663, miR-512-3p and miR-371-5p) are mainly responsible for the dysregulation of STAT3 and hence can provide an opportunity for early detection of metastasis and development of alternative therapeutic approaches." (PMID 28005952, 2016). "We next tested whether expression of STAT3 and p14ARF can serve as novel prognostic markers predicting the risk of BCR and metastatic disease progression." (PMID 26198641, 2015).
metastatic disease (continued). "In a previous attempt, our group studied the role of signal transducer and activator of transcription 3 (STAT3) in PCa, which turned out to exert tumor suppressor activities: Mice with a deletion of both Pten and Stat3 in the prostate epithelium develop aggressive metastatic tumors." (PMID 32323921, 2020). "Mechanistic data uncover a novel PDE1A/YTHDF2/STAT3 axis driving NSCLC metastasis and suggest potential therapeutic strategies for metastatic disease." (PMID 40704992, 2025). "In vivo studies demonstrated a reduced number of liver metastatic tumors in mice injected with CENPN knockdown cells, with decreased expression levels of CENPN, p-STAT3, and USP37." (PMID 40458725, 2025). "The inhibition was found to reduce phosphorylation of extracellular signal-regulated kinase (ERK) and signal transducer and activator of transcription 3 (STAT3) and showed potential to assist with the control of metastatic disease." (PMID 36559044, 2022). "This sensitization to hormone therapy was attributed to reduced STAT3, Notch3 and CD133 expression in metastatic tumor cells." (PMID 35053592, 2022). "The decreased STAT-3 phosphorylation and increased SHP-1 expression were also shown in isolated peritoneal metastatic tumors." (PMID 22937084, 2012). "The expression of p-STAT3, STAT3, MMP-2, and MMP-9 in metastatic tumors by western blot analysis." (PMID 34526411, 2021).